CGGBP1 (CGG triplet repeat binding protein 1)
Description:
Binds to nonmethylated 5'-d(CGG)(n)-3' trinucleotide repeats in the FMR1 promoter. May play a role in regulating FMR1 promoter.
Synonyms: CGGBP; p20-CGGBP
Tractability: PROTAC: ubiquitination databases record sites on it; its protein half-life has been measured.
Gene: Protein-coding gene on chromosome 3 (88,051,944 to 88,149,885, reverse strand). Ensembl gene ENSG00000163320.
Subcellular location: Nucleus
Subcellular location (Human Protein Atlas): Nucleoplasm
Gene Ontology:
Molecular function: DNA-binding transcription factor binding; double-stranded DNA binding; identical protein binding; protein binding
Biological process: epigenetic regulation of gene expression; negative regulation of transcription by RNA polymerase II; regulation of gene expression; regulation of transcription by RNA polymerase II
Cellular component: nucleoplasm; nucleus
Genetic constraint (gnomAD): Loss-of-function variants: 4 observed, 11.93 expected, observed/expected ratio (o/e) 0.34, 90% interval 0.16 to 0.77. The upper end of that interval is the gene's LOEUF score, 0.77, which puts it in group 3 of 6, group 1 being the genes least tolerant of losing a copy. Missense variants: 135 observed, 212.03 expected, observed/expected ratio (o/e) 0.64, 90% interval 0.55 to 0.73. Synonymous variants: 76 observed, 78.74 expected, observed/expected ratio (o/e) 0.97, 90% interval 0.8 to 1.17.
Homologues: Orthologues: chimpanzee CGGBP1 (100% identical), dog CGGBP1 (100% identical), pig CGGBP1 (100% identical), rat Cggbp1 (100% identical), guinea pig CGGBP1 (99% identical), macaque CGGBP1 (99% identical), mouse Cggbp1 (98% identical).
Diseases named in the same sentence as CGGBP1 in open-access papers:
CGGBP1 is named in the same sentence as 10 diseases in open-access papers, as found by Europe PMC text mining. Sharing a sentence is not in itself a finding about the gene and the disease. The quoted sentences say what the papers report.
colon cancer (1 paper, 2011). "We compared the effects of CGGBP1 siRNA in HCT116 human colon cancer cell lines either WT or deficient for CDKN1A." (PMID 21733196, 2011).
glioma (1 paper, 2011). A benign or malignant brain and spinal cord tumor that arises from glial cells (astrocytes, oligodendrocytes, ependymal cells). "In this study, we used the same protocol of siRNA mediated knockdown of CGGBP1 to deplete CGGBP1 in the human glioma cell line U-2987 MG." (PMID 21733196, 2011).
metabolic syndrome (1 paper, 2021). A cluster of metabolic risk factors for CARDIOVASCULAR DISEASES and TYPE 2 DIABETES MELLITUS. "Therefore, altered CGGBP1 may be a critical indicator of the misalignment between the central and peripheral circadian clocks which could progressively induce metabolic syndrome and increase the risk of mood disorders." (PMID 34916903, 2021).
mood disorder (1 paper, 2021). A cognitive disorder a disturbance in which the person's mood is hypothesized to be the main underlying feature. "However, due to the scarcity of studies on the association between CGGBP1 and psychiatric disorders, the involvement of CGGBP1 in mood disorders is yet to be identified." (PMID 34916903, 2021).
ovarian carcinoma (1 paper, 2012). A malignant neoplasm originating from the surface ovarian epithelium. "In some cases it was shown only decreased expression (LOC285205, EPHB1 and RBSP3 (CTDSPL)) and in other cases loss of heterozygosity and copy number changes (CGGBP1 and RBSP3 (CTDSPL)) in ovarian cancer." (PMID 23202957, 2012).
post-traumatic stress disorder (1 paper, 2021). An anxiety disorder precipitated by an experience of intense fear or horror while exposed to a traumatic (especially life-threatening) event. "Reduced CGGBP1 gene expression had been reported in the peripheral blood of patients with post-traumatic stress disorder." (PMID 34916903, 2021).
cancer (5 papers, 2011 to 2024). A tumor composed of atypical neoplastic, often pleomorphic cells that invade other tissues. "In cancer cells however, which often have various abnormalities in the cell cycle regulatory mechanisms, function of CGGBP1 is unknown and is of obvious interest since loss of cell cycle regulation is an event central to tumorigenesis." (PMID 21733196, 2011). "Within this cluster, we found a high expression of the proto‐oncogene MYBL2, as well as of CGGBP1, which regulates the cell cycle in cancer cells." (PMID 39167619, 2024). "CGGBP1 expression in cancer cells is responsive to stress and depletion of CGGBP1 leads to a stress response-like gene expression pattern." (PMID 33081720, 2020). "The human protein atlas and the cancer genome atlas describe the widespread expression of CGGBP1 mRNA and protein in normal cells as well as a variety of cancers." (PMID 33081720, 2020). "A small-compound inhibition of functions of CGGBP1 would be a valuable tool in cancer biology research." (PMID 33081720, 2020). "By applying our screening method we have identified that the HDAC inhibitor anti-cancer agent Givinostat also inhibits CGGBP1-DNA binding." (PMID 33081720, 2020). "In this study, we combined CGGBP1 knockdown by siRNA with different genetic mutations of various cell cycle regulatory genes to rigorously test how CGGBP1 regulates cell cycle in cancer cells." (PMID 21733196, 2011). "Our results show new functions for CGGBP1 in cell cycle, in regulation of expression of CDKN1A and GAS1, and provide insights into how CGGBP1 depletion overrides the redundancies of checkpoint escape mechanisms present in different cancer cells." (PMID 21733196, 2011). "Of all the previously known functions of CGGBP1, its role in transcription has been evaluated here for the G0/G1 arrest phenotype observed in cancer cells in this study." (PMID 21733196, 2011). "The differential dependence of normal and cancer cells on CGGBP1 suggests that inhibiting it may be a useful means to target cancer cells." (PMID 33081720, 2020). "Our results necessitate investigations into expression and function of CGGBP1 in cancers." (PMID 21733196, 2011). "In this study we explored the role of CGGBP1 in the cell cycle in various cancer cell lines." (PMID 21733196, 2011). "CGGBP1 thus regulates cell cycle through multiple parallel mechanisms and further studies on its mechanisms of action will be important in understanding how cancer cell proliferation could be controlled." (PMID 21733196, 2011). "We selected novel epigenetic markers including NKIRAS1/RPL15, THRB RBPS3 (CTDSPL), IQSEC1, NBEAL2, ZIC4, LOC285205, CGGBP1, EPHB1 and FOXP1 that allowed detection of cancer in ovarian biopsies on all stages with sensitivity equal to (72 ± 11)% and specificity (94 ± 5)%." (PMID 23202957, 2012). "Interestingly, a variety of cancer cell types exhibit a dependence on CGGBP1 that resembles the non-oncogene addiction phenomenon described for heat shock stress and proteotoxic stress response genes, some of which are regulated by CGGBP1." (PMID 33081720, 2020).
Tumor (2 papers, 2011 to 2018). "CGGBP1 depletion by RNA interference in tumor-derived cells caused an increase in the cell population at G0/G1 phase and reduced the number of cells in the S phase." (PMID 21733196, 2011).
neurological diseases (1 paper, 2016). "An example of TAF15 mRNA turnover target involved in transcriptional control and also neurological diseases is the CGG-binding protein 1 (CGGBP1), which binds to CGG repeats in the promoter of the fragile X mental retardation 1 (FMR1) gene resulting in reduced expression." (PMID 27378374, 2016).
CGGBP1 also shares sentences with these, for which no sentence is quoted: psychiatric disorder (1 paper).